BRD4 (bromodomain containing 4)
Diseases named in the same sentence as BRD4 in open-access papers (continued):
Sharing a sentence is not in itself a finding about the gene and the disease.
medulloblastoma (continued). "Chemical inhibition of BRD4 with JQ1 was sufficient to inhibit growth of medulloblastoma cells in vitro and in vivo." (PMID 24796395, 2014). "We are now pursuing further studies to more clearly understand the role of BRD4 function in medulloblastoma and the application of BRD4 inhibition in clinically relevant models." (PMID 24796395, 2014). "Here we show that targeting BRD4 either pharmaceutically with JQ1 or by siRNA knockdown was effective at reducing the viability of medulloblastoma cell lines." (PMID 24231268, 2013). "We therefore assessed BRD4 expression in primary medulloblastomas and normal cerebellar tissue, as a control." (PMID 24231268, 2013). "All medulloblastoma subgroups strongly expressed BRD4, with the highest expression detected in the shh subgroup." (PMID 24231268, 2013). "High-level BRD4 expression were detected in 99 of 115 pediatric primary medulloblastomas (75%) and in both adult medulloblastoma samples (I-III)." (PMID 24231268, 2013). "Since siRNA-mediated depletion of the BRD2 BET protein has been described to reduce transcription of cyclin D1 in human cells, we investigated the result of siRNA-mediated BRD4 knockdown on CCND1 regulation in medulloblastoma cells." (PMID 24231268, 2013). "We also evaluated BRD4 expression in a panel of medulloblastoma cell lines that included HD-MB3, ONS-76, UW-228, Daoy, D-341 and D-283." (PMID 24231268, 2013). "Functional evidence from our ORF screen analysis further highlights the biological relevance of BRD4 deregulation in other cancer types, such as medulloblastoma, where targeted therapies against BRD4, including bromodomain and extra-terminal motif-bromodomain inhibitors, hold clinical promise." (PMID 40112818, 2025). "In a high-throughput drug screen, BRD4 inhibitors have been found to be one of the two classes of compounds exerting the best synergistic anticancer effects with the CDK4/CDK6 inhibitor Ribociclib in medulloblastoma cells." (PMID 38135679, 2023). "Furthermore, Venkataraman's study demonstrated that BRD4 inhibition by JQ1 treatment in medulloblastoma induced apoptosis leading to a significant decrease in cell proliferation." (PMID 28484091, 2017). "BRD4 was depleted in 2 medulloblastoma cell lines using shRNA." (PMID 24796395, 2014). "Taken together, BRD2, BRD3 and BRD4 are expressed in primary medulloblastomas." (PMID 24231268, 2013). "BRD4 was immunohistochemically detected in samples from 115 primary medulloblastomas from pediatric patients, 14 cerebellum samples previously arrayed into a tissue microarray and 2 samples from primary medulloblastomas from adult patients." (PMID 24231268, 2013). "A fourth case was included as a low-score match to group 3 medulloblastoma in the initial paper describing the Heidelberg version 11 methylation classifier, but which in our analysis of the Heidelberg version 12 classifier, matched to CNS embryonal tumor with BRD4::LEUTX fusion." (PMID 38500181, 2024). "Furthermore two recent reports also show the utility of BRD4 inhibition in medulloblastoma." (PMID 24796395, 2014). "Specifically, the BRD4 inhibitor, JQ1, was shown to reduce the proliferation of group 3 medulloblastoma cells with MYC amplification and to prolong the survival of mouse models with tumors having these characteristics." (PMID 37568705, 2023). "BRD4 facilitates MYC-mediated transcriptional activation and as such has been explored as a potential therapeutic target in MYC driven medulloblastoma." (PMID 29880060, 2018). "Further genetic inhibition of BRD4 with shRNA phenocopied the JQ1 treatment and significantly decreased neurosphere formation of medulloblastoma cells." (PMID 24796395, 2014). "Taken together, BRD4 knockdown reduced both MYC expression and viability in the group 3-derived medulloblastoma cell line, HD-MB3, and therefore, phenocopies the effects of JQ1 treatment." (PMID 24231268, 2013).
medulloblastoma (continued). "Inspection of methylation signatures using UMAP for the four NIH cases and 2 of the previously published cases fore which (IDAT) files were available showed that CNS tumors with BRD4::LEUTX fusion cluster together, near but separate from group 3 medulloblastoma." (PMID 38500181, 2024). "Notably, JQ1, a BRD4 inhibitor, was shown to inhibit the SHH-mediated proliferation of several tumors, including medulloblastomas, and to overcome their resistance to SMO antagonists." (PMID 37568705, 2023). "In addition, treatment of a medulloblastoma mouse model with I-BET151, a Brd4 inhibitor, reduced Gli1 expression, cell proliferation and tumor growth, indicating epigenetics drives Hh activation in cancer." (PMID 29563577, 2018). "Expression of BRD4 is not increased in medulloblastoma samples compared to normal cerebellum further suggesting the activity of JQ1 is due to BRD4 mediated, c-MYC driven signaling." (PMID 24796395, 2014). "BRD2 and BRD4 were both expressed in all primary medulloblastomas in this medulloblastoma cohort, however, expression was not significantly higher than in cerebellar tissue." (PMID 24231268, 2013). "BRD4 was recently shown to insulate chromatin from DNA damage signalling, indicating that combining DNA-damaging agents with BET inhibitors, such as JQ1, may increase DNA damage response in medulloblastoma cells." (PMID 24231268, 2013). "However, it is unclear whether these inhibitors can be given to children suffering from medulloblastoma, as we do not fully understand the role of Brd4 during normal development." (PMID 31292434, 2019). "Unlike a previous study implying that elevated BRD4 expression mediates SMOi resistance by activating Gli1 transcription, we report that JQ1 inhibition suppresses SMOi-resistant SHH medulloblastoma in the absence of significant Gli1 expression." (PMID 36688010, 2022).
non-small cell lung carcinoma (19 papers, 2015 to 2025). A group of at least three distinct histological types of lung cancer, including non-small cell squamous cell carcinoma, adenocarcinoma, and large cell carcinoma. "Inhibition of BRD4 reduces Pulmonary Hypertension Resulting from Combined Hypoxia and Pulmonary Inflammation, inhibited the growth of non-small cell lung carcinoma via AKT activation." (PMID 41280641, 2025). "For instance, small nucleolar RNA host gene 18 (SNHG18) promotes the proliferation and metastasis of non-small cell lung cancer (NSCLC) by regulating the expression of bromodomain containing 4 (BRD4)." (PMID 35149697, 2022). "Furthermore, mkl1-induced SNHG18 regulates the metastasis and growth of non-small cell lung cancer by modulating the miR-211-5p/BRD4 pathway." (PMID 35359593, 2022). "BRD4 has been shown to promote non-small cell lung cancer progression." (PMID 34400879, 2021). "It has been demonstrated that high level of BRD4 promotes non-small cell lung cancer progression." (PMID 28545522, 2017). "BRD4 inhibition by JQ1 has been demonstrated to control EMT and reduce migration and invasion abilities of human non-small cell lung cancer cells." (PMID 28545522, 2017). "In non-small cell lung cancer, SE promote TGFβ-induced EMT by enhancing the expression of EMT-related transcription factors, while a BRD4-specific inhibitor JQ1 can inhibit SE-driven transcription of ETS2, HNF4A, JUNB, and other genes, resulting in the obstruction of EMT process." (PMID 39915455, 2025). "About the signaling pathway involved in miR-211-5p, the miR-211-5p/CENPK axis in tongue squamous cell carcinoma and the miR-211-5pp/BRD4 axis in non-small cell lung cancer have been reported, but not about resistance mechanisms." (PMID 35311096, 2022). "Compared with non-small cell lung cancer, KEAP1 and BRD4 expression were much higher in SCLC cells than in NSCLC cells based on publicly available RNA-seq data from Cancer Cell Line Encyclopedia (CCLE) and microarray data from Genomics of Drug Sensitivity in Cancer (GDSC)." (PMID 35453346, 2022).
Ewing sarcoma (17 papers, 2016 to 2025). A small round cell tumor that lacks morphologic, immunohistochemical, and electron microscopic evidence of neuroectodermal differentiation. "Although low-dose HDAC inhibitors did not affect the level of EWS::FLI1 in our experiments, proteomic analyses identified that HDAC inhibitors do reduce the level of the BRD4 protein in Ewing sarcoma cell lines." (PMID 40478628, 2025). "In PDX models of Ewing sarcoma, treatment with the BRD4 inhibitor NHWD870 and the IGF1R inhibitor BMS754807 results in substantial and durable anticancer effects, while monotherapy was much less effective." (PMID 38135679, 2023). "BRD4 has been shown to interact with EWS-FLI1, and BRD4 inhibition by BET inhibitors results in reduced cell growth in Ewing’s sarcoma cells." (PMID 36194562, 2022). "This is in striking contrast to the bromodomains of BRD4 which are a dependency in both synovial and Ewing sarcoma cells, as well as several other malignancies." (PMID 30431433, 2018). "In conclusion, our results shed light on the BET bromodomains’ role, especially BRD4′s one, as essential regulators of Ewing Sarcoma carcinogenesis." (PMID 27006472, 2016). "To directly assess the relevance of targeting BET bromodomain proteins signaling in Ewing Sarcoma disease, we first evaluated the messenger RNA expression level of BRD2, BRD3 and BRD4 in ten human Ewing Sarcoma cell lines." (PMID 27006472, 2016). "This redistribution of BRD4 could further disrupt the function of BRD4 in Ewing sarcoma cells and exacerbate the effects of HDAC inhibitors on the decrease of BRD4 protein levels." (PMID 40478628, 2025). "In Ewing Sarcoma, co-immunoprecipitation revealed an interaction of BRD4 with CDK9." (PMID 35883603, 2022). "BET inhibitors (BETi), such as JQ1, have demonstrated antitumor activity in several fusion-driven sarcomas, including rhabdomyosarcoma (RMS) and Ewing sarcoma (ES), by disrupting BRD4-dependent transcriptional activity, reducing oncogene expression (e.g., MYC), and impairing super-enhancer function." (PMID 41166819, 2025). "In support of this, in Ewing sarcoma, the EWSR1‐FLI1‐induced de novo super‐enhancers and oncogenic transcriptional programmes were disrupted and repressed by BRD4 inhibition or depletion." (PMID 35182012, 2022). "Remarkably, appreciable amounts of EWS-FLI1 and EWS-ERG proteins were found in a large transcriptional complex consisting of BRD4, MED1, and RNA-Pol2 in Ewing sarcoma cells." (PMID 30903020, 2019). "BRD4 is reported to support cell proliferation in multiple cancer types, and analysis of Dependency Map (Broad Institute) data identified that reducing BRD4 levels, by shRNA knockdown or CRISPR knockout, inhibits the proliferation of Ewing sarcoma and other cancer cell lines." (PMID 40478628, 2025). "In addition, FLAG-tagged AHDC1 expression partially co-localized with BRD4 and BRG1 in Ewing’s sarcoma cells." (PMID 36194562, 2022). "We hypothesize that AHDC1 might be one of the accessory proteins needed to stabilize BRD4, BRG1, and probably EWS-FLI1 in Ewing’s sarcoma cells." (PMID 36194562, 2022). "In Ewing sarcoma cell lines and patient-derived xenograft (PDX) lines, AKT pathway activation protects Ewing sarcoma cells against BRD4 inhibitors, and IGF1R inhibitors and mTOR inhibitors suppress AKT pathway activation and synergistically enhance cancer cell sensitivity to BRD4 inhibitors." (PMID 38135679, 2023). "This reversal of EWS/FLI gene expression pattern was exclusively mirrored through siRNA-mediated knockdown of BRD3 and BRD4 but not BRD2, suggesting that BRD3 and BRD4 may be critical epigenetic regulators in Ewing sarcoma." (PMID 27635231, 2016).
cervical carcinoma (16 papers, 2016 to 2025). A carcinoma arising from either the exocervical squamous epithelium or the endocervical glandular epithelium. "BRD4 gene overexpression has been linked with a growth-inhibition phenotype in HeLa cervical cancer cells, but the effects of gene overexpression across multiple cancer types has not been systematically interrogated." (PMID 40112818, 2025). "In particular, there are also few studies on the mechanism of BRD4 involvement in the carcinogenesis and development of cervical cancer." (PMID 38410799, 2024). "A study found that miR-152-5p was down-regulated and BRD4 was up-regulated in cervical cancer tissues." (PMID 38410799, 2024). "JQ1 (a BRD4 inhibitor) sensitized cervical cancer to radiation therapy by suppressing RAD51AP1 transcription." (PMID 37914994, 2023). "Low expression of miR-152-5p was detected in cervical carcinoma tissue samples from patients, while the expression of BRD4 was relatively low." (PMID 34299149, 2021). "Similarly, JQ1, a small molecule inhibitor of bromodomain or extraterminal domain (BET) protein BRD4, downregulates E6 and E7 transcription and was shown to render otherwise chemo-resistant cervical cancer cells vulnerable to cisplatin in vitro." (PMID 33668328, 2021). "Interestingly, transfection of the miR-152-5p inhibitor could at least partly reverse the regulatory effect of apigenin on cervical carcinoma cells, while overexpressed BRD4 exerted a similar effect." (PMID 34299149, 2021). "Studies in cervical cancer have shown that BRD4 inhibitors can enhance the response of tumor cells to chemotherapy by inhibiting the expression of HPV16 E6, and are thus expected to be potential new targets for cervical cancer therapy." (PMID 38410799, 2024). "Inhibition of BRD4 reduces RAD51AP1 transcription and sensitizes cervical cancer to radiation." (PMID 37035213, 2023). "We also examined an additional six cervical carcinoma derived cell lines (C-33A, C-411, CasKi, HeLa, ME-180 and SiHa) for a prominent Brd4 focus but none was apparent." (PMID 29364907, 2018).
squamous cell carcinoma (16 papers, 2012 to 2026). A carcinoma arising from squamous epithelial cells. "The recent development of potent and highly specific Kac competitive inhibitors for BET BRDs provides a compelling case for targeting these BRDs for the treatment of an extremely aggressive subtype of squamous cell carcinoma that is caused by chromosomal rearrangement of BRD3 or BRD4 with NUT." (PMID 22464331, 2012). "We observed that high level of BRD4 more frequently appeared in patients with squamous cell carcinomas, with lymph node metastasis, with TNM stages III–IV and with low differentiation." (PMID 26840017, 2016). "A recent publication also confirmed that MYC is a key downstream target of BRD4-NUT, associated with an aggressive form of squamous cell carcinoma." (PMID 25989842, 2015). "BRD4's role in cancer was initially appreciated when the presence of a fusion protein was identified in a very aggressive form of squamous cell carcinoma." (PMID 24796395, 2014). "These inhibitors have also shown promising results for an incurable, genetically-defined NUT-midline human squamous carcinoma, defined by the presence of acquired chromosomal rearrangements involving BRD4-NUT fusion genes." (PMID 24260471, 2013). "BRD4::NUTM1 aberrantly activates transcription factors (TFs) associated with basal progenitor cells of stratified epithelium, resulting in a poorly differentiated squamous cell carcinoma (SCC) phenotypes." (PMID 41266112, 2026). "In addition, BRD4 is upregulated in squamous cell carcinoma and can promote the growth and proliferation of squamous cell carcinoma cells." (PMID 34876902, 2021). "In NUT (nuclear protein in testis) midline carcinoma (NMC), a highly aggressive subtype of squamous cell cancer, BRD4–NUT fusion oncoprotein enhances the interaction of p300 and BRD4, leading to a massive feed-forward expansion of transcriptionally inactive hyperacetylated chromatin domains." (PMID 34540900, 2021). "BRD4, as a member of the bromodomain and extra terminal domain (BET) family of bromodomain-containing proteins, is also a proto-oncogene that can be mutated via chromosomal translocation in a rare form of squamous-cell carcinoma, although the role in NSCLC has not been described." (PMID 26840017, 2016).